IL6 (interleukin 6)
Diseases named in the same sentence as IL6 in open-access papers (continued):
Sharing a sentence is not in itself a finding about the gene and the disease.
glioma (continued). "In summary, these data strongly demonstrate that the mesenchymal transformation of glioma cells induced by RTVP-1 is, at least partly, mediated by the IL-6 pathway." (PMID 26267319, 2015). "Overexpression of the STAT3 DN in the U87 glioma cells abrogated the increased promoter activity and the expression of RTVP-1 induced by IL-6." (PMID 26267319, 2015). "Since the number of GBMs with high WNK2 expression is very limited (only 4 of 248 cases with log2 median-intensity value > 0), we grouped high and low-grade gliomas in order to assess the correlation of WNK2 levels with MMPs and IL6 expression." (PMID 25596741, 2015). "Further analysis using STRING identified four main gene networks (IL-6, BCL2, PTGS2 and CXCR4) that were downregulated in glioma cells silenced for RTVP-1." (PMID 26267319, 2015). "The resistance of gliomas to apoptosis, induced in one scenario by TNF-α, is possibly due to the release of cytokines IL-6, IL-8, and MCP-1, in fact, in response to TNF-α treatment." (PMID 25411122, 2014). "Our group showed that conditioned medium from glioma cells increased STAT3 activity in microglia cells, resulting in overexpression of IL-6 and IL-10 and downregulation of IL-1β." (PMID 23864876, 2013). "Furthermoe, the levels of several NF-κB target genes, TNF-α, IL-6, CCND1, MYC, BcL-XL and MMP-9, were upregulated in Bmi-1-overexpressing, but downregulated in Bmi-1-silenced glioma cells." (PMID 23383216, 2013). "In conclusion, the present data indicated prognostic significance of Cygb in gliomas: correlation with PI3K, Akt, IL-6, TNFα, VEGF, microvessel morphometry and survival of patients with gliomas." (PMID 23688241, 2013). "TGFβ is shown to be involved in CD44 regulation in breast CSC maintenance while interleukin 6 (IL6) can promote growth and survival of glioma stem cells." (PMID 24091605, 2013). "In the present study, our results suggest that IL-1β induces IL-6 release through the IκB-NFκB pathway, p38 MAP kinase, SAPK/JNK and JAK-STAT3 pathway in C6 glioma cells." (PMID 21682888, 2011). "Intriguingly, glioma-intrinsic TIM-3 has been shown to regulate not only the malignant behaviors of glioma cells but also the recruitment and polarization of macrophages toward an anti-inflammatory and pro-tumorigenic state via a TIM-3/IL-6 signaling axis." (PMID 41486149, 2026). "Interestingly, expression of the pro-inflammatory genes IL6 and TNF increased in grade II-III gliomas compared to control microglia, but decreased in GBM, highlighting the dynamic nature of TAM-MG gene expression during tumor progression." (PMID 38895459, 2025). "Interestingly, it regulates IL6 and CCL5 expression in glioma cells, exacerbating the neuroinflammatory process." (PMID 39962586, 2025). "This study aimed to investigate the relationship between serum inflammatory markers (TNF-α, IL-6, CRP) and cerebrospinal fluid (CSF) cytokine levels (AVP, OT, β-EP) with the severity of postoperative neurological injury and prognosis in patients with glioma." (PMID 41394380, 2025). "Similar to IL-33 and its downstream mediator IL-6, CD276 may have a role in the activation of STAT3 downstream signaling, which enhances stem-like characteristics in glioma cells and induces an anti-inflammatory phenotype in TAMs." (PMID 40136662, 2025). "In vitro research using murine BV2 microglial cells demonstrated that conditioned media from glioma cells might activate microglial cells by increasing the mRNA levels of cyclooxygenase-2 (COX-2), tumor TNF-α, IL-6, iNOS, and IL-1β." (PMID 40727443, 2025). "Differential gene analysis and subsequent GSEA identified potential association of F3-T3 with various cancer-related pathways, including the interleukin 6-janus kinase-STAT3 (IL6-JAK-STAT3) pathway, indicating its role in the malignant progression of glioma cells." (PMID 40265014, 2025). "Furthermore, overexpression of CSMD1 in glioma cell lines suppressed the aggressive phenotype and TNF/P65/IL-6 and IL-8/STAT3 pathways." (PMID 38561856, 2024).
glioma (continued). "GLIPR1 could promote migration and invasion of glioma and epithelial-mesenchymal transition by mediating signal transducer and activator of transcription 3 (STAT3) pathway and IL-6." (PMID 38368374, 2024). "Blocking of the IL-6-mediated JAK2/STAT3 pathway could substantially suppress the proliferation and promote the apoptosis of glioma cells." (PMID 38715108, 2024). "A recent meta-analysis proposed that circulating interleukin 6 (IL-6) and C-Reactive Protein (CRP) could potentially serve as robust biomarkers for predicting poor prognosis in patients with glioma." (PMID 38784036, 2024). "Similarly, the mRNA expression levels of STAT3, IL-6, and TNF-α, which are crucial factors in the STAT3 pathway, were elevated in glioma tissues compared to paracancerous tissues." (PMID 38495483, 2024). "GSEA enrichment analysis pinpointed the signaling pathways implicating SOCS1 in glioma patients, indicating that high SOCS1 expression in the CGGA glioma samples correlates with allograft rejection, programmed cell death, IL-6 and JAK-STAT3 signaling pathways, and interferon-gamma responses." (PMID 39654174, 2024). "The results from RT-PCR demonstrated a notable upsurge in the expression of two M1 macrophage markers—TNF-α and IL-6—in non-GBM gliomas." (PMID 38283752, 2023). "Gliomas with high TANK levels exhibited enrichment in immunomodulatory pathways, including “hypoxia”, “angiogenesis”, “inflammatory response”, “NF-kappaB signaling”, and “IL6/STAT3 signaling” in the TCGA cohort." (PMID 37215097, 2023). "Furthermore, circulating IL-6 and CRP have the potential to act as potent prognostic biomarkers for unfavorable outcomes in glioma patients." (PMID 38259287, 2023). "CGGA data analysis revealed that high levels of IL-18 or IL-6 mRNA predict a poor prognosis for glioma patients (data not shown)." (PMID 37734869, 2023). "The glioma resection surgery increased the levels of proinflammatory cytokines (e.g., TNF-α, IL-6) in the brain, which promoted the recruitment of systemic administrated ND-MMSNs to the residual glioma site, improved survival rate, and delayed glioma relapse in the surgically treated glioma mice." (PMID 37111742, 2023). "In glioma, TFAP2A disturbs the expression of stemness-related genes, such as NANOG, SOX2 and CD133, via both directly binding the regulation region of NANOG and indirectly interfering with the IL6/JAK2/STAT3 signaling pathway." (PMID 37291585, 2023). "Important factors expressed by TAMs in gliomas include TNF-ß, high levels of interleukins 6 and 10 (Il-6, Il-10), MMP2 and MMP9, and VEGF and VEGA, which collectively promote glioma proliferation and invasion, angiogenesis and suppression of T effector cell and NK cell activity." (PMID 38275375, 2023). "Glioma cell-derived IL-6 activated STAT3, which upregulated IL-6 expression in astrocytes." (PMID 36923251, 2023). "In gliomas, TMEM44-AS1 binds to SerpinB3 and activates myc and EGR1\IL-6 signaling." (PMID 38040698, 2023). "IL6, IL17, TWEAK, and VEGF signaling pathways induce glioma cell proliferation and migration." (PMID 35855654, 2022). "The enhanced invasion may be mediated by an IL-6-induced increase in STAT3 signaling and upregulation of MMP2 in glioma cells." (PMID 34503065, 2021). "IL‐6, CXCL1 and TGFβ2 play an important role in glioma radiotherapy resistance." (PMID 34216174, 2021). "Our studies suggest that stromal-derived factor 1α (SDF-1α), EGF, platelet-derived growth factor β (PDGFβ), and IL-6 are key microglia-derived mediators of Pyk2 and FAK activation in primary human glioma cell lines, leading to increased invasion and proliferation." (PMID 34944779, 2021). "Additionally, glioma-derived CCL2 recruits TAMs to the tumor, but at the same time takes part in a feed-forward mechanism, where it induces IL-6 production in microglia, which consecutively affects glioma cells by increasing their invasiveness." (PMID 34503065, 2021).
glioma (continued). "Additionally, expression levels of CD133, IL6 and TGF-β were found to serve as prognosis markers of glioma patients." (PMID 33576874, 2021). "Indeed, treatments with IL-6 and EGF activated Pyk2 and FAK phosphorylation in all evaluated glioma cell lines, while the effect of PDGFβ, SDF-1α, and IL-8 was patient dependent." (PMID 34944779, 2021). "Finally, the expression of IL-6 in gaMSC subpopulations and its effects on FOXS1 expression in glioma cells were also investigated." (PMID 34256854, 2021). "IL-6 and miR-155-3p promote tumorigenesis in glioma cells, but their functions in TAMs are still not clear." (PMID 33828078, 2021). "In addition to immunosuppressive functions, GAMs promoted the migration, angiogenesis, and invasion of gliomas via TGF-β2, IL-6, and VEGF, which were affected by glioma cell metabolism as well." (PMID 34211978, 2021). "In response to these signals, GAMs release multiple cytokines such as transforming growth factor ß (TGF-β), stress-inducible protein 1 (STI-1), prostaglandin E2 (PGE2), IL-6, IL-1β, IL-10, and epidermal growth factor (EGF), which promote glioma cell proliferation and inhibit T cells function." (PMID 34084145, 2021). "Moreover, Pearson’s correlation analyses among clinical glioma specimens revealed significant positive correlations between HOXB5 and IL6 expression in each WHO grade glioma and among the total glioma samples." (PMID 33858489, 2021). "Our data suggest that IL-6, mainly originating from CD90low gaMSCs, could increase the expression of FOXS1 in glioma cells and induce TMZ resistance." (PMID 34256854, 2021). "Also, the levels of IL-6 found in serum and cerebrospinal fluid obtained from GBM patients increases according with glioma grade and significantly decreases upon surgery." (PMID 33902430, 2021). "Moreover, IL-6 also increased cell proliferation, migration and invasion by activating JAK2/STAT3 signaling pathway in human glioma cells." (PMID 34165442, 2021). "CD90low gaMSCs could increase FOXS1 expression in glioma cells by IL-6 secretion, thereby activating epithelial-mesenchymal transition and resistance to TMZ in glioma cells." (PMID 34256854, 2021). "Recent studies have suggested that several factors, released by glioma cells but not exclusively, can induce the proliferation, differentiation, and recruitment of MDSCs, such as IL-6, GM-CSF, IL-10, prostaglandin-E2 (PGE2), VEGF, and TGF-β." (PMID 33766119, 2021). "Targeting of IL6 signaling suppresses CSC survival and tumor growth in glioma." (PMID 33576874, 2021). "Similarly, overall survival was lower in patients with high expression of both IL6 and CD133 in their glioma samples and in the TCGA database than in other patients." (PMID 33576874, 2021). "Similar to IL-6, knockdown of TMEM44-AS1 reduced the expression of EGR1 in LN-18 and U251 cells, whereas TMEM44-AS1 overexpression increased EGR1 expression in SF126 glioma cells." (PMID 34696771, 2021). "Glioma-derived CCL2 acts on microglia with CCR2 and then produces IL-6 to stimulate the glioma." (PMID 33511267, 2020). "Second, it is not easy to maintain glioma cells in a TNF-α/IL-6/sIL-6R contained micro-environment in the rat brain for differentiation therapy." (PMID 33227992, 2020). "Following a 24 hours incubation of hEGFRvIII:CD3 bi-scFv, PBMCs, and human glioma cells U87-MG-EGFRvIII or control U87-MG cells, we harvested the supernatant and measured the concentration of IFN-ɣ, IL-6, IL-1β, MIP-1α, GM-CSF, and TNFα using the Luminex multiplex platform." (PMID 32273346, 2020). "M1 and M2 play opposite roles, while M1 plays anti-tumor effects, M2 phenotype has an immunosuppressive effect and secretes TGF-B, IL-6, IL-1B, EGF, and other cytokines to promote the growth, invasion, and expansion of gliomas by stimulating tumor-related blood vessel formation and tumor metastasis." (PMID 33511267, 2020). "Nevertheless, after pretreating C6 glioma cells with recombinant IL-6 protein, no obvious differentiation was observed." (PMID 33227992, 2020).
glioma (continued). "In 63 adult patients with gliomas and 31 healthy controls, the expressions of TREM-1 and TREM-2 on CD14+ blood cells (method: flow cytometry) and the levels of soluble sTREM-1, HMGB1, IL-6, and IL-10 (Elisa tests) were analyzed." (PMID 32684831, 2020). "IL-6, TNF-α, and IL-12 are markers of M1-type macrophages that can repress glioma progression." (PMID 33363140, 2020). "Several factors that are synthesized and released by microglia/TAMs have been reported to increase the invasion of glioblastomas or glioma, such as stress-inducible protein 1 (STI1), epidermal growth factor (EGF), IL-6, and MT1-MMP (membrane type 1-matrix metalloproteinase)." (PMID 33330047, 2020). "On the other hand, our results showed that circulating IL‐6 [HR 1.10 (95% CI: 1.05‐1.16; P = .000)] and CRP [HR 2.02 (95% CI: 1.52‐2.68; P = .000)] levels were highly correlated with a poor overall survival (OS) rate in glioma patients." (PMID 31599129, 2019). "In conclusion, our meta‐analysis suggested that circulating IL‐6 and CRP levels may serve as powerful biomarkers for a poor prognosis in glioma patients." (PMID 31599129, 2019). "Admittedly, there are other known cytokines that activate STAT3, e.g. IL-4 and -13, and therefore the dependence of our results on IL-6 effect alone is not confirmed as of yet, as it requires validation in other glioma cell lines outside of the ones we tested." (PMID 31361777, 2019). "All of these suggest that MALAT1 dependent EV-mediated microglia stimulation and IL-6, IL-8, and TNF-α secretion could contribute to glioma progression." (PMID 32117213, 2019). "Moreover, the tumor suppressive effect of AP-2α was exerted through inhibiting the transcriptional activity of the Nanog gene and the IL6/STAT3 signaling pathway to attenuate the stemness and TMZ resistance of glioma cells." (PMID 31534499, 2019). "Our current results showed that AP-2α could downregulate IL6 expression and block the Jak2/STAT3 signaling pathway in glioma." (PMID 31534499, 2019). "Determination of the levels of circulating IL‐6 and CRP might aid in predicting the clinical outcome in glioma patients." (PMID 31599129, 2019). "Moreover, intragastric administration of PHOR in a dose of 1.5 g/kg BW to a nude mouse model of glioma remarkably slowed glioma growth and increased the levels of TNF-α, IL-1β, and IL-6 through the activation of PI3K/AKT signaling." (PMID 31281578, 2019). "In addition, our results show a reduction in the levels of proinflammatory cytokines, such as IFN-γ, IL-6, and TNF-α in simvastatin-treated C6 glioma cell line." (PMID 30524484, 2018). "Therefore, in the present study, we examined the role of IL6 and IL6R along with their regulatory factors in gliomas." (PMID 29258522, 2017). "Next, we examined the expression of IL6 and IL6R in patient-derived primary glioma cells." (PMID 29258522, 2017). "We also observed an increase in IL-6 and CXCL1 expression in MCs co-cultured with glioma cells." (PMID 28445977, 2017). "Moreover, compared with the IDH-mutant gliomas, the levels of IL6 and IL6R mRNA expression were higher in IDH-wildtype gliomas." (PMID 29258522, 2017). "In gliomas, the NFAT1/IL6/IL6R pathway may mediate crosstalk between tumours and immune cells resulting in a tumour-promoting inflammatory microenvironment." (PMID 29258522, 2017). "We first examined IL6 and IL6R mRNA expression in clinical gliomas using TCGA dataset." (PMID 29258522, 2017). "Moreover, silencing of IL-6 downregulated the expression of the mesenchymal marker vimentin in the HF2355 and HF2490 GSCs and inhibited cell migration of U87 glioma cells and of the HF2490 and HF2303 GSCs." (PMID 26267319, 2015). "Co-targeting of IL-6 and VEGF was found to potently inhibit glioma growth and invasiveness, implying that IL-6 production in response to cancer therapy may contribute to the invasiveness of recurrent tumors." (PMID 26513016, 2015).
glioma (continued). "Glioma cells expressing EGFRvIII were found to recruit EGFR-WT-expressing cells and accelerate glioma tumorigenicity by up-regulating the expression levels of cytokines (e.g., interleukin 6 [IL6] and/or leukemia inhibitory factor)." (PMID 25992628, 2015). "For human glioma, inhibition of IRE1α resulted in down-regulating of VEGF-A, IL-1β, IL-6, and IL-8." (PMID 26633383, 2015). "In summary, these results strongly suggest that RTVP-1 mediates the mesenchymal transformation of glioma cells, at least partly, via the IL-6 pathway and points to the existence of positive regulatory pathways linking RTVP-1 and IL-6 via the activation of the STAT3 pathway." (PMID 26267319, 2015). "For this analysis we treated A172 glioma cells and the HF2354 GSCs with IL-6 and found that this treatment upregulated the expression of the mesenchymal markers vimentin and FN in these cells, increased cell migration of the A172 cells and of the GSCs, HF2354 and HF2359." (PMID 26267319, 2015). "C6 glioma cells were incubated for 6 h in the absence of either cytokine (control) and in the presence of IL-1β, IL-6, or both." (PMID 25311416, 2014). "A negative correlation between Rcor2 and Il6 gene expression was also verified in LPS-treated C6 glioma cells." (PMID 25051986, 2014). "Therefore, the first goal of this study was to determine Cygb, PI3K, phosphorylated (p)-Akt, IL-6, TNFα and VEGF expression in gliomas." (PMID 23688241, 2013). "We immunohistochemically evaluated the expression of Cygb, phosphatidylinositol-3 kinase (PI-3K), phosphorylated (p)-Akt, Interleukin-6 (IL-6), tumor necrosis factor-α (TNFα) and vascular endothelial growth factor (VEGF) in 88 patients with 41 high-grade gliomas and 47 low-grade gliomas." (PMID 23688241, 2013). "Therefore, based on these findings, it is probable that IL-1β induces IL-6 release through activation of the IκB-NFκB pathway, p38 MAP kinase, SAPK/JNK and JAK-STAT3 pathway in C6 glioma cells." (PMID 21682888, 2011). "In addition, the presence of glioma appears to increase the Th17-inducing cytokines, TGF-β and IL-6." (PMID 21060663, 2010). "Recently, it has been reported that subtoxic levels of H2O2 stimulate the expression and release of IL-6 in fibroblasts, mast cells, skeletal myocytes, and trabecular cells, but not in glioma cells or bronchial epithelial cells." (PMID 21031020, 2010). "In addition, TNF-α (10 ng/ml) significantly induced IL-6 mRNA expression at 6 h after stimulation, thus suggesting that TNF-α stimulates the synthesis of IL-6 in C6 glioma cells." (PMID 20205746, 2010). "TNF-α induces IL-6 release through the phosphorylation of NFκB, p38 mitogen-activated protein (MAP) kinase and stress-activated protein kinase (SAPK)/c-Jun N-terminal kinase (JNK) in rat C6 glioma cells." (PMID 20205746, 2010). "Furthermore, mRNA for the Th17-inducing cytokines, IL-6 and TGF-β, as well as the Th17-activating cytokine, IL-23, is expressed in immunocompetent mice with glioma." (PMID 21060663, 2010). "In addition, alcohol may regulate the expression of immunosuppressive cytokines, such as IL-6 and TNF-α, which could affect the glioma microenvironment and inhibit tumor initiation and progression." (PMID 39940440, 2025). "In addition, a Kaplan–Meier (KM) survival analysis was conducted on the core genes in liver cancer, renal clear cell carcinoma, and glioma, and it was found that TNF, IL6, IFNG, and NR1H4 in liver cancer and TNF and IL1B in renal clear cell carcinoma were associated with survival prognosis." (PMID 40238193, 2025). "Notably, there was overexpression of various cytokines, including IL-1β, IL-4, IL-6, IL-8, IL-10, TGF-β and TNF in the patient cohort, which was unsurprising given that these cytokines serve primarily immunosuppressive roles in the glioma microenvironment." (PMID 41034696, 2025).